BECN2 (beclin 2)
Description:
Involved in 2 distinct lysosomal degradation pathways: acts as a regulator of autophagy and as a regulator of G protein-coupled receptors turnover. Regulates degradation in lysosomes of a variety of G protein-coupled receptors via its interaction with GPRASP1/GASP1.
Synonyms: BECN1L1; BECN1P1
Tractability: No criterion of Open Targets' tractability assessment is met for any kind of drug.
Gene: Protein-coding gene on chromosome 1 (241,957,767 to 241,959,062, forward strand). Ensembl gene ENSG00000196289.
Subcellular location: Cytoplasm
Gene Ontology:
Molecular function: protein binding; phosphatidylinositol 3-kinase binding; protein-macromolecule adaptor activity; protein-containing complex binding
Biological process: autophagy; endosome to lysosome transport; G protein-coupled receptor catabolic process; cellular response to nitrogen starvation; late endosome to vacuole transport; mitophagy; receptor catabolic process
Cellular component: phosphatidylinositol 3-kinase complex, class III, type I; phosphatidylinositol 3-kinase complex, class III, type II; cytoplasm
Genetic constraint (gnomAD): Loss-of-function variants: 0 observed, 1.56 expected, observed/expected ratio (o/e) 0, 90% interval 0 to 1.53. That is too few expected variants to judge how well the gene tolerates losing a copy. Missense variants: 428 observed, 446.46 expected, observed/expected ratio (o/e) 0.96, 90% interval 0.88 to 1.04. Synonymous variants: 173 observed, 182.9 expected, observed/expected ratio (o/e) 0.95, 90% interval 0.83 to 1.07.
Homologues: Orthologues: chimpanzee BECN2 (97% identical), macaque BECN2 (89% identical), pig BECN2 (59% identical), rabbit BECN2 (59% identical), tropical clawed frog becn1 (54% identical), mouse Becn2 (53% identical), rat Becn2 (52% identical), zebrafish becn1 (48% identical), dog BECN2 (47% identical), Drosophila melanogaster Atg6 (36% identical), Caenorhabditis elegans bec-1 (26% identical). Paralogues in human: BECN1 (56% identical).
Diseases named in the same sentence as BECN2 in open-access papers:
BECN2 is named in the same sentence as 12 diseases in open-access papers, as found by Europe PMC text mining. Sharing a sentence is not in itself a finding about the gene and the disease. The quoted sentences say what the papers report.
Obesity (2 papers, 2016 to 2022). Accumulation of substantial excess body fat. "Because the genetic locus of BECN2 is also linked to diabetic related traits in multiple ethnic groups in human, BECN2 likely represents an important genetic determinant of human obesity and diabetes." (PMID 35832792, 2022).
cerebral infarction (1 paper, 2021). An ischemic condition of the brain, producing a persistent focal neurological deficit in the area of distribution of the cerebral arteries. "Transfection with miR-122 Agomir into N2a cells increased cell viability and reduced the levels of apoptotic and autophagic proteins such as casp-3, Bax, LC3B-II and Beclin-2 mediating neuroprotective effects against cerebral infarction." (PMID 34684090, 2021).
Hyperglycemia (1 paper, 2020). An increased concentration of glucose in the blood. "Hyperglycemia inhibits Jun N-terminal kinase (JNK) signaling and enhances the interaction between Beclin-1 and Beclin-2 resulting in autophagy inhibition." (PMID 32455017, 2020).
lymph node metastasis (1 paper, 2015). "We found that negativity of Beclin 1 was associated with poor recurrence free survival, yet positivity of Beclin 2 was linked to poor prognostic factors, including positive lymphovascular status and lymph node metastasis." (PMID 26506105, 2015). "Positive nuclear expression of Beclin 2 was connected to poor prognostic factors, including lymph node metastasis and lymphovascular invasion." (PMID 26506105, 2015).
lymphoma (1 paper, 2025). A malignant (clonal) proliferation of B- lymphocytes or T- lymphocytes which involves the lymph nodes, bone marrow and/or extranodal sites. "Existing research indicates that heterozygous loss of Beclin 2 leads to autophagy defects, and supplementing the genetic deficiency of Beclin 2 can inhibit the progression of lymphoma." (PMID 39735677, 2025). "Moreover, Beclin 2 interacts with STX5 to promote the fusion of ATG9A-mediated vesicles with autophagosomes, degrading MEKK3 and thus suppressing the development of lymphoma." (PMID 39735677, 2025).
Oral Cancer (1 paper, 2015). "In this study, we investigated the expressions of Beclin 1 and Beclin 2 in oral cancer tissues, and examined the associations among expressions of Beclin 1 and Beclin 2, clinicopathologic features, and survival rates." (PMID 26506105, 2015). "The oral cancer tissues exhibited variable cytoplasmic expressions of Beclin 1 and Beclin 2, ranging from total loss to diffuse strong expression." (PMID 26506105, 2015). "Relationships between Beclin 1 and Beclin 2 expressions and clinicopathologic variables in 195 cases of oral cancer." (PMID 26506105, 2015). "To inspect the effect of Beclin 2 depletion and its relationship with autophagy in oral cancer, we transfected siRNAs targeting either beclin 2 or Atg5 in SAS cells." (PMID 26506105, 2015). "In oral cancer cells, overexpression of either Beclin 1 or Beclin 2 led to autophagy activation and increased clonogenic survival; knockdown of Beclin 2 impaired autophagy and increased clonogenic survival." (PMID 26506105, 2015). "We disclosed that oral cancer patients with either high or low expression of Beclin 2 showed poorer prognosis than those with moderate expression." (PMID 26506105, 2015). "Only a small subset of oral cancer tissues expresses nuclear staining of Beclin 1 (33/195, 16.92%) and Beclin 2 (29/195, 14.87%)." (PMID 26506105, 2015). "To evaluate Beclin 1 and Beclin 2 expressions and their subcellular localization, we performed immunohistochemistry on 195 cases of oral cancer tissues and normal oral mucosas." (PMID 26506105, 2015). "We investigated Beclin 1 and Beclin 2 expressions by immunohistochemistry in 195 cases of oral cancer." (PMID 26506105, 2015). "The aims of this study were to analyze Beclin 1 and Beclin 2 expressions in oral cancer tissues and in cell lines, and to evaluate their possible roles in cancer progression." (PMID 26506105, 2015). "Beclin 2 functional analyses further showed either its depletion or overexpression promoted tumor growth in the SAS oral cancer cells." (PMID 26506105, 2015). "The cytoplasmic Beclin 1 and Beclin 2 expressions were unrelated in oral cancer tissues." (PMID 26506105, 2015). "To investigate the effects of Beclin 1 and Beclin 2 overexpression in oral cancer, we used SAS cells transfected with plasmid expressing flag-tagged Beclin 1 and Beclin 2, respectively." (PMID 26506105, 2015).
cancer (2 papers, 2015 to 2021). A tumor composed of atypical neoplastic, often pleomorphic cells that invade other tissues. "Antimalarial drugs promote mitochondrial apoptosis through block the apoptosis regulator (Beclin-2 protein), thereby promoting the apoptosis of cancer cells." (PMID 34553648, 2021). "Either high or low Beclin 2 expression in cancer tissues suggested dysfunction in autophagy and metabolism." (PMID 26506105, 2015). "In this study, we first evaluated the expression and prognostic role of Beclin 2 in human cancer." (PMID 26506105, 2015). "The association of Beclin 2 and cancer has not been addressed, and the relationship between Beclin 2 and Beclin 1 expression and the outcomes of cancer patients have never been studied." (PMID 26506105, 2015).
tumor (2 papers, 2015 to 2019). "The tumor growth caused by Beclin 2 depletion may be evoked by autophagy and/or autophagy-independent mechanisms." (PMID 26506105, 2015). "The tumor progression caused by Beclin 2 overexpression and depletion may be due to different mechanisms." (PMID 26506105, 2015). "Loss of Beclin 2 may cause accumulation of some GPCRs and lead to tumor progression." (PMID 26506105, 2015). "We compared Beclin 1 and Beclin 2 expressions with age, sex, tumor size, lymph node status, metastasis, stage, grade, lymphovascular invasion, and necrosis." (PMID 26506105, 2015). "The impacts of Beclin 1 and Beclin 2 on autophagy and tumor growth were evaluated by conversion of LC3-I to LC3-II and by clonogenic assays, respectively." (PMID 26506105, 2015). "Beclin 1 overexpression, as well as Beclin 2 overexpression and depletion, contributed to tumor growth." (PMID 26506105, 2015). "Either overexpression or depletion of Beclin 2 promoted tumor cell growth." (PMID 26506105, 2015). "Furthermore, our study first established the connection of Beclin 2 and tumor progression." (PMID 26506105, 2015). "Although we found that manipulations of Beclin 1 or Beclin 2 level did lead to change in autophagy, their effects on tumor growth may not entirely directly due to autophagy." (PMID 26506105, 2015).
BECN2 also shares sentences with these, for which no sentence is quoted: Insulin resistance (2 papers); bladder cancer (1); breast tumors (1); diabetes (1).